FZD4 (frizzled class receptor 4)
Description:
Receptor for Wnt proteins. Most frizzled receptors are coupled to the beta-catenin (CTNNB1) canonical signaling pathway, which leads to the activation of disheveled proteins, inhibition of GSK-3 kinase, nuclear accumulation of beta-catenin (CTNNB1) and activation of Wnt target genes. Plays a critical role in retinal vascularization by acting as a receptor for Wnt proteins and norrin (NDP) (By similarity). In retina, it can be activated by Wnt protein-binding and also by Wnt-independent signaling via binding of norrin (NDP), promoting in both cases beta-catenin (CTNNB1) accumulation and stimulation of LEF/TCF-mediated transcriptional programs (By similarity). A second signaling pathway involving PKC and calcium fluxes has been seen for some family members, but it is not yet clear if it represents a distinct pathway or if it can be integrated in the canonical pathway, as PKC seems to be required for Wnt-mediated inactivation of GSK-3 kinase. Both pathways seem to involve interactions with G proteins. May be involved in transduction and intercellular transmission of polarity information during tissue morphogenesis and/or in differentiated tissues.
Synonyms: Fz-4; hFz4; CD344; EVR1; FEVR; FZD4S; Fz4; FzE4; GPCR
Tractability: Small molecule: a structure with a bound ligand is known. Antibody: UniProt places it where antibodies can reach, with high confidence; its Gene Ontology location is reachable by antibodies, with high confidence; UniProt predicts a signal peptide or a membrane-spanning region; the Human Protein Atlas places it where antibodies can reach. PROTAC: UniProt records ubiquitination sites on it.
Target class: Frizzled family G protein-coupled receptor; Membrane receptor
Gene: Protein-coding gene on chromosome 11 (86,945,679 to 86,955,395, reverse strand). Ensembl gene ENSG00000174804.
Subcellular location: Cell membrane
Subcellular location (Human Protein Atlas): Plasma membrane; Nucleoplasm; Primary cilium
Pathways (Reactome):
Signal Transduction: Asymmetric localization of PCP proteins; Ca2+ pathway; Class B/2 (Secretin family receptors); Regulation of FZD by ubiquitination; WNT5A-dependent internalization of FZD4
Vesicle-mediated transport: Cargo recognition for clathrin-mediated endocytosis; Clathrin-mediated endocytosis
Disease: Signaling by RNF43 mutants
Gene Ontology:
Molecular function: amyloid-beta binding; cytokine binding; cytokine receptor activity; PDZ domain binding; protein binding; protein heterodimerization activity; protein homodimerization activity; protein-containing complex binding; ubiquitin protein ligase binding; Wnt receptor activity; signaling receptor activity; Wnt-protein binding; transmembrane signaling receptor activity
Biological process: canonical Wnt signaling pathway; negative regulation of cell-substrate adhesion; Norrin signaling pathway; positive regulation of cell migration; positive regulation of DNA-templated transcription; positive regulation of transcription by RNA polymerase II; retina vasculature morphogenesis in camera-type eye; Wnt signaling pathway, calcium modulating pathway; cellular response to retinoic acid; neuron differentiation; non-canonical Wnt signaling pathway; positive regulation of neuron projection arborization; Wnt signaling pathway; cell surface receptor signaling pathway; cerebellum vasculature morphogenesis; cytokine-mediated signaling pathway; extracellular matrix-cell signaling; positive regulation of dendrite morphogenesis; retinal blood vessel morphogenesis
Cellular component: cell surface; plasma membrane; clathrin-coated endocytic vesicle membrane; dendrite; cell-cell junction; glutamatergic synapse; membrane; synapse
Genetic constraint (gnomAD): Loss-of-function variants: 16 observed, 39.6 expected, observed/expected ratio (o/e) 0.4, 90% interval 0.27 to 0.61. The upper end of that interval is the gene's LOEUF score, 0.61, which puts it in group 2 of 6, group 1 being the genes least tolerant of losing a copy. Missense variants: 599 observed, 709.52 expected, observed/expected ratio (o/e) 0.84, 90% interval 0.79 to 0.9. Synonymous variants: 246 observed, 268.38 expected, observed/expected ratio (o/e) 0.92, 90% interval 0.82 to 1.02.
Gene-disease validity (ClinGen):
ClinGen rates the evidence that FZD4 causes each of these diseases.
FZD4-related exudative vitreoretinopathy (autosomal dominant): Definitive. Any exudative vitreoretinopathy caused by a variant in the FZD4 gene.
Homologues: Orthologues: chimpanzee FZD4 (99% identical), dog FZD4 (99% identical), rabbit FZD4 (99% identical), guinea pig FZD4 (98% identical), pig FZD4 (98% identical), rat Fzd4 (97% identical), mouse Fzd4 (97% identical), macaque FZD4 (97% identical), tropical clawed frog fzd4 (90% identical), zebrafish fzd4 (80% identical), Drosophila melanogaster fz4 (36% identical), Caenorhabditis elegans lin-17 (33% identical). Paralogues in human: FZD10 (53% identical), FZD9 (51% identical), FZD2 (45% identical), FZD1 (45% identical), FZD7 (44% identical), FZD8 (43% identical), FZD5 (43% identical), FZD3 (34% identical), FZD6 (33% identical), SMO (26% identical), SFRP4 (15% identical), FRZB (15% identical), and 3 more.
Diseases named in the same sentence as FZD4 in open-access papers:
FZD4 is named in the same sentence as 102 diseases in open-access papers, as found by Europe PMC text mining. Sharing a sentence is not in itself a finding about the gene and the disease. The quoted sentences say what the papers report.
Familial exudative vitreoretinopathy (43 papers, 2007 to 2025). Familial exudative vitreoretinopathy (FEVR) is a rare hereditary vitreoretinal disorder characterized by abnormal or incomplete vascularization of the peripheral retina leading to variable clinical manifestations ranging from no effects to minor anomalies, or even retinal detachment with blindness. "The diagnosis of familial exudative vitreoretinopathy (FEVR) due to an FZD4 mutation was confirmed by whole-exome sequencing and validated with Sanger sequencing." (PMID 41204464, 2025). "WNT2B binds Frizzled4 (Fzd4), and Fzd4 signaling is linked with familial exudative vitreoretinopathy in humans and in mice with incomplete development of retinal vasculature." (PMID 37048106, 2023). "FZD4 (frizzled-type receptor 4) was reported to be associated in certain PHPV cases as well as a gene linked to familial exudative vitreoretinopathy (FEVR)." (PMID 34485332, 2021). "Norrin-FZD4 interaction is primarily observed in retinal angiogenesis, linking FZD4 mutations to familial exudative vitreoretinopathy (FEVR)." (PMID 34604862, 2021). "The panel test found a heterozygous missense variant NM_012193.3:c.313A>G, p.(Met105Val) in FZD4, which has been associated with AD familial exudative vitreoretinopathy." (PMID 31836858, 2020). "Mutations in NDP and FZD4 have been closely related to a series of retinal diseases including familial exudative vitreoretinopathy (FEVR)." (PMID 32420371, 2020). "In humans, a large number of missense mutations in FZD4 results in a variable amount of retinal hypovascularization, a condition called familial exudative vitreoretinopathy (FEVR)." (PMID 30849938, 2019). "Mutations in FZD4 have been identified as a cause of familial exudative vitreoretinopathy and have been confirmed in cases worldwide." (PMID 22355249, 2012). "A missense mutation, p.Pro33Ser in frizzled homolog (Drosophila) 4 (FZD4), previously suggested as a disease-causing variant in familial exudative vitreoretinopathy, was determined to be a rare benign polymorphism." (PMID 21179236, 2010). "Familial exudative vitreoretinopathy (FEVR) is an inherited childhood blinding disorder with close to 85% of molecularly determined cases due to rare variants in the genes encoding members of the frizzled 4 (FZD4) receptor complex." (PMID 41448433, 2025). "The identification of a heterozygous, dominant FZD4 variant (p.Pro251Arg) in a patient with familial exudative vitreoretinopathy (FEVR) raises questions about how the FZD5 p.Pro267Leu variant, affecting the same conserved amino acid, leads to a recessive phenotype." (PMID 39503780, 2024). "In particular, dystrobrevin alpha, encoded by DTNA, is causally involved in Barth syndrome, a severe infantile cardiomyopathy, and Frizzled-4 protein, a receptor for Wnt proteins, encoded by FZD4, is causally involved in familial exudative vitreoretinopathy leading to an avascular peripheral retina." (PMID 35053288, 2022). "Whether ERG is implicated in human ocular diseases, including Norrie disease and familial exudative vitreoretinopathy, which are associated with Fzd4 and its ligand Norrin, remains to be established." (PMID 25584796, 2015). "In humans, two rare pediatric eye diseases, familial exudative vitreoretinopathy (FEVR) and X-linked Norrie disease, correspond to the loss-of-function mutations in Norrin/Fzd4/LRP5 axis and/or several other genes and norrin (Ndp) gene, respectively." (PMID 37887287, 2023). "This case series investigates if variants in the FZD4 gene are associated with familial exudative vitreoretinopathy (FEVR) with extraocular features." (PMID 35951321, 2022). "Are FZD4 variants associated with familial exudative vitreoretinopathy (FEVR) with extraocular features?" (PMID 35951321, 2022). "Familial exudative vitreoretinopathy (FEVR) is a nonsyndromic autosomal dominant retinal disorder commonly caused by variants in the FZD4 gene." (PMID 35951321, 2022).
Familial exudative vitreoretinopathy (continued). "Fzd4 loss-of-function mutations have been linked to familial exudative vitreoretinopathy (FEVR), a disease characterized by abnormal retinal vasculature." (PMID 22938389, 2012). "Mutations in the CTD of FZD4, that encompasses the K-T/S-XXX-W, a PDZ binding motif and S/T-X-V PDZ recognition motif, are associated with familial exudative vitreoretinopathy (FEVR), underscoring the functional importance of its unique structural features." (PMID 40376615, 2025). "Mutation in the LDLR5 receptor and FZD4 causes Familial Exudative Vitreoretinopathy (FEVR)." (PMID 34039417, 2021). "In the retina, FZD4 and the ligand NDP are critical mediators of signalling and are mutated in familial exudative vitreoretinopathy." (PMID 28675177, 2017). "Mutations in human genes NDP, FZD4, LRP5 and TSPAN12 cause familial exudative vitreoretinopathy, a potentially blinding disease initially characterized by retinal hypovascularization." (PMID 28675177, 2017). "Mutations in candidate genes that encode for a ligand (NDP) and receptor complex (FZD4, LRP5 and TSPAN12) in the Norrin β-catenin signaling pathway are involved in the pathogenesis of familial exudative vitreoretinopathy (FEVR, MIM # 133780)." (PMID 27316669, 2016). "Loss-of-function mutations in Norrin (an unconventional Wnt ligand), Wnt receptor Frizzled 4 (FZD4) or co-receptor LRP5, can cause familial exudative vitreoretinopathy (FEVR) in humans." (PMID 20652025, 2010). "Norrie disease and familial exudative vitreoretinopathy (FEVR) are both hereditary eye disorders characterised by aberrant and incomplete retinal vascular development, and are associated with mutations in Fzd4, which has been linked to ERG expression in other angiogenesis-associated disease." (PMID 35723257, 2022). "Mutations in FZ-CRD of Frizzled class receptor 4 (FZD4) and Muscle, skeletal, receptor tyrosine kinase (MuSK) and Receptor tyrosine kinase-like orphan receptor 2 (ROR2) cause Familial Exudative Vitreoretinopathy (FEVR), Congenital Myasthenic Syndrome (CMS), and Robinow Syndrome (RS) respectively." (PMID 31892318, 2019). "FZD4 gene is well understood among all members of the family in terms of its biological role and involvement in disease, therefore we sought to infer the protein structural basis for familial exudative vitreoretinopathy (FEVR) phenotype caused by mutations in this gene." (PMID 30849938, 2019). "In humans, mutations in NDP, FZD4, LRP5 or TSPAN12 genes are linked to familial exudative vitreoretinopathy (FEVR), which is characterized by retinal vascular defects, vision impairment, or blindness." (PMID 28675177, 2017). "Loss-of-function mutations in Norrin, FZD4, LRP5 and Tspan12 all cause familial exudative vitreoretinopathy (FEVR) in humans." (PMID 24058663, 2013). "Disease contexts in which this mechanism is likely relevant include familial exudative vitreoretinopathy (FEVR), which is a retinal vascular disease caused by impaired norrin/FZD4 signaling, for example by mutations in the human TSPAN12 gene." (PMID 41086024, 2025). "Mutations in Norrin, Fzd4, LRP5, β-catenin, and Tspan12 are associated with inherited diseases of the retinal vasculature, most notably familial exudative vitreoretinopathy (FEVR), and therapeutic targeting of Norrin/β-catenin signaling shows promise for modulating the BRB and BBB." (PMID 39745873, 2025). "Norrie's disease and familial exudative vitreoretinopathy (FEVR) are retinal conditions, which present similarly to ROP engendered, engendered by a single genetic variant many of which overlap with ROP including NDP, FZD4 TSPAN12, and LRP5 from our analysis." (PMID 37492605, 2023). "The literature has also described the case report of a child affected by 22q11.2DS, presenting familial exudative vitreoretinopathy (FEVR), in the absence of the pathognomonic mutations LRP5 and FZD4." (PMID 39202748, 2024).
Familial exudative vitreoretinopathy (continued). "FZD4, LRP5, or TSPAN12 mutations are also the causes of a spectrum of related congenital retinopathies such as osteoporosis-pseudoglioma syndrome, familial exudative vitreoretinopathy (FEVR), and Coats disease, each of which share resembling phenotypes with Norrie disease." (PMID 36432666, 2022).
Norrie disease (15 papers, 2013 to 2025). A rare X-linked genetic vitreoretinal condition characterized by abnormal retinal development with congenital blindness. "The genes mutated in these diseases include NDP (norrin) in Norrie disease and FZD4, LRP5, and TSPAN12 in FEVR." (PMID 41086024, 2025). "The role of C1q in BRB function is likely relevant in the context of FEVR and Norrie disease, related inherited diseases caused by impaired norrin/FZD4 signaling." (PMID 41086024, 2025). "Many of the ocular findings in OPPG patients overlap with those of FEVR and ND, caused by loss-of-function mutations in other Wnt signaling components, such as Frizzled-4 (FZD4) and Norrie disease protein (NDP)." (PMID 27031698, 2016). "Norrin/Frizzled 4 (FZD4) signaling is disrupted in Norrie disease, resulting in irregular vasculature and BRB/BBB leakage in the retina and the brain." (PMID 40508141, 2025). "Pathogenic mutations in NDP and FZD4 lead to a number of retina-related diseases including FEVR, Norrie disease, persistent hyperplastic primary vitreous, advanced stage of retinopathy of prematurity, and Coats disease." (PMID 31827910, 2019). "The cause of inadequate norrin signalling in FEVR and Norrie disease is a primary deficiency due to a genetic mutation in the norrin- > FZD4, LRP5/6, TSPAN12 signalling pathway, affecting retinal vascular development beginning in utero." (PMID 35651932, 2022). "However, individuals with X-linked FEVR, autosomal dominant FEVR, retinopathy of prematurity, and Norrie disease have also been reported to have mutations in NDP and FZD4 genes." (PMID 34485332, 2021). "PPI analysis has indicated that FZD4 protein interactome via PLIN2 as well as the MAP kinase signaling pathway to be a likely link bridging the functional relationship between retinoschisis and Norrie disease." (PMID 34039417, 2021). "There is increasing awareness that the clinical phenotype known as Norrie disease may not be exclusive to mutations in the NDP gene and there is a strong case for recessively inherited FZD4 mutations as a candidate gene in unsolved cases." (PMID 35651932, 2022).
ovarian carcinoma (11 papers, 2014 to 2023). A malignant neoplasm originating from the surface ovarian epithelium. "For instance, circ_0004712 deficiency impeded proliferation and metastasis of ovarian cancer cells through the crosstalk with miR-331-3p/FZD4 axis." (PMID 37173768, 2023). "HAGLR also plays a role in the miR-130a-3p/SOX4 (SRY-box 4) axis in liver cancer and in the miR-608/FZD4 (frizzled class receptor 4) axis in ovarian cancer." (PMID 37624034, 2023). "Generally, HOXD4-AS1 exerts tumor-promoting functions through the miR-608/FZD4 axis in ovarian cancer." (PMID 35387124, 2022). "Upregulation of HOXD-AS1 expression in ovarian cancer (OC) competitively binds miR-608, an inhibitory miRNA of Fzd4, in vitro and in vivo, leading to high Fzd4 expression that correlates with ovarian cancer cell migration, invasion, and proliferation." (PMID 34671643, 2021). "HOXD-AS1 modulates the miR-130a/E2F8 (E2F transcription factor 8) axis in glioma, the miR-130a-3p/SOX4 (SRY-box 4) axis in liver cancer, and the miR-608/FZD4 (frizzled class receptor 4) axis in ovarian cancer." (PMID 29702599, 2018). "Intriguingly, we identified NDP, FZD4, and TSPAN12 to be associated with a delayed tumor progression, thus pointing to a novel tumor suppressor function of this signaling pathway in ovarian cancer." (PMID 27215396, 2016). "Interestingly, FZD4 is reported to be upregulated in ovarian cancer, and FZD4 is a transmembrane protein that belongs to the β-catenin signaling pathway." (PMID 35387124, 2022).
prostate carcinoma (11 papers, 2011 to 2022). A carcinoma that arises from epithelial cells of the prostate gland. "The aberrantly upregulated expression of the gene was observed in various human cancers, such as prostate cancer and bladder cancer.The upregulation of FZD4 expression was associated with tumor proliferation, migration and invasion, which was mediated by Wnt/β-catenin pathway." (PMID 35174106, 2022). "ERG often co-overexpressed with FZD4 in prostate cancer, which led to cancer-promoting phenotypic effects, such as EMT and loss of cell adhesion." (PMID 29789460, 2018). "miR-377 also controls the proliferation, apoptosis, migration, and invasion in metastatic prostate cancer cells by targeting FZD4 whereas miR-101 suppresses the WNT5a-induced proliferation of lung fibroblasts by targeting FZD4/6." (PMID 30574422, 2018). "FZD4 expression was higher in androgen-independent and metastatic prostate cancer cell lines, while FZD2 was upregulated in hormone-depleted LNCaP cells, similar to WNT11." (PMID 29717114, 2018). "Activation of WNT signaling by FZD4 was found in ERG [Erythroblast transformation-specific (ETS)-related gene]-positive prostate cancers." (PMID 29789460, 2018). "miR-377 was shown to target FZD4, a gene important for epithelial-to-mesenchymal transition and to affect migration and invasion in prostate cancer cells." (PMID 25889255, 2015). "For instance, FZD4 promotes the formation of EMT phenotypes in prostate cancer." (PMID 33832493, 2021). "Furthermore, several genes including FZD4, OPRK1 and OXTR identified here with a growth inhibitory loss-of-function impact on the prostate cancer cells have been recently associated in independent studies with a role in prostate cancer pathogenesis." (PMID 21443765, 2011). "In contrast, FZD4 and PTK7 levels were similar (low and high, respectively) in prostate and prostate cancer." (PMID 29717114, 2018). "FZD4 (frizzled family receptor 4), a receptor for Wnt proteins, is a mediator of ERG oncogene–induced Wnt signaling and epithelial-to-mesenchymal transition in human prostate cancer cells." (PMID 28792525, 2017). "In line with our data, a link between Fzd4 and ERG has been previously observed in prostate cancer." (PMID 25584796, 2015). "FZD4, FZD8, and PTK7, but not FZD2, were more highly expressed in prostate cancer than in benign or normal prostate tissue." (PMID 29717114, 2018). "FZD4 mRNA levels were upregulated in prostate tumor datasets but FZD4 silencing did not affect Wnt-11 activation of ATF-2-dependent transcription and FZD4 did not colocalize with Wnt-11, so FZD4 is unlikely to transduce Wnt-11 signals in prostate cancer." (PMID 29717114, 2018).